NOTCH1 (notch receptor 1)
Diseases named in the same sentence as NOTCH1 in open-access papers (continued):
Sharing a sentence is not in itself a finding about the gene and the disease.
gastric cancer (continued). "In gastric cancer (GC) patients, both tumor tissue and peripheral blood showed significantly higher expression of Notch receptor (NOTCH1, NOTCH2) mRNA than normal human gastric tissue, and they also had higher proportions of Treg cells and Th17 cells." (PMID 37131214, 2023). "The current understanding is that the Notch signal pathway, especially Notch1/Notch2 signaling, has an oncogenic effect on stomach cancer." (PMID 35382168, 2022). "Suppression of Notch1 can reverse the multidrug resistance of gastric cancer cells by inhibiting the expression of multidrug resistance-associated protein Hes." (PMID 35655918, 2022). "The attenuated angiogenesis mediated by Xiaotan Sanjie decoction that comprised eleven herbs (including Pinelliae rhizome, Rhizoma arisaematis, and Poria cocos) in gastric cancer was related to the Notch-1/VEGF and IL-8/VEGF/VEGFR signaling axis." (PMID 35784750, 2022). "NALT1 overexpression activates Notch 1 expression in both gastric cancer and pediatric T cell acute lymphoblastic leukemia." (PMID 36229883, 2022). "Luteolin, another component of MO, which has been found to reduce gastric cancer cells growth and cancer metastasis in vitro and in vivo via regulating Notch1, PI3K, AKT, mTOR, ERK, STAT3, and P38 signaling pathways." (PMID 35889404, 2022). "In conclusion, the findings of the study showed that ETSJC improved the chemosensitivity of 5-FU by blocking Notch1/Hes1 signaling pathway in gastric cancer-bearing mice." (PMID 34257696, 2021). "Viability of the gastric cancer cells after linc00641 siRNA and Notch-1 cDNA cotransfection was then detected by MTT assay." (PMID 33714199, 2021). "Studies have shown that activation of Notch1 and Notch2 in gastric cancer tissues aggravates gastric cancer progression." (PMID 34234838, 2021). "In summary, linc00641 exerts its functions partly by targeting the miR-429/Notch-1 axis in gastric cancer." (PMID 33714199, 2021). "MiR-449c-5p was a hub for circ-NOTCH1 to promote metastasis and stemness of gastric cancer cells, leading to the disease progression of gastric cancer." (PMID 34987577, 2021). "We concluded that linc00641 promoted the malignant progression of gastric cancer by modulating the miR-429/Notch-1 axis." (PMID 33714199, 2021). "We found that linc00641 promoted the malignant progression of gastric cancer cells by targeting miR-429 and increasing the expression of Notch-1." (PMID 33714199, 2021). "A study of gastric cancer patients detected a high frequency of mutations in MLL4, ERBB3, FBXW7, MLL3, mtor(RPTOR), NOTCH1, PIK3CA, KRAS, ERBB4 and EGFR." (PMID 33909629, 2021). "Notch-1 is also involved in the regulation of gastric cancer stem self-renewal activity and 5-FU resistance." (PMID 33714199, 2021). "The latest evidence shows that luteolin affects cell proliferation, migration, apoptosis and reverses EMT by inhibiting Notch1 pathway, thereby inhibiting the progression of gastric cancer." (PMID 34422902, 2021). "In gastric cancer, high DLL4 levels reasonably resulted in hyperactivation of Notch1 signaling and were associated with poorer clinical outcome, stem-cell-like phenotype and 5-FU resistance." (PMID 34680255, 2021). "Downregulation of Notch-1 by siRNA transfection repressed gastric cancer cell viability and abolished the linc00641 overexpression-induced promotion of cell viability." (PMID 33714199, 2021). "Notch-1 increases the cisplatin resistance of gastric carcinoma cells via the upregulation of the lncRNA AK022798." (PMID 33714199, 2021). "According to our findings, gastric cancer tissues, compared with adjacent normal tissues presented a higher level of expression of Notch1/2/3." (PMID 32028262, 2020). "Based on this background, we supposed that lncRNA SNHG1 promotes EMT in gastric cancer cells via the miR-15b-regulated DCLK1/Notch1 axis." (PMID 32423385, 2020).
gastric cancer (continued). "Compared to GES-1 cells, Notch1 RNA and protein expression was higher in the various gastric cancer cells, whereas Notch2 expression was variable." (PMID 32117763, 2020). "We also performed a survival analysis and noted that gastric cancer patients with high transcription levels of Notch1/2/3/4 had a low relapse-free survival." (PMID 32028262, 2020). "DAPT has been shown to inhibit cell proliferation, migration, and invasion of gastric cancer by inhibiting the Notch1/Hes1 pathway, and in line with the study results, decreased expression of mesenchymal markers such as vimentin and Snail in gastric cancer." (PMID 31508369, 2019). "Luteolin is a flavonoid extracted from green plants that was found to inhibit VM tube formation in gastric cancer through downregulating the Notch1-VEGF signaling pathway." (PMID 31772665, 2019). "Notch1 is considered a potential target of bELE because CD44+ gastric cancer stem‐like cells proliferate faster than their CD44− counterparts and express a higher level of Notch1." (PMID 28297578, 2017). "miR124 is reported to inhibit cell growth, migration and invasion of gastric cancer cells and interfere with the cell cycle by targeting Jagged1 and thus negatively regulating Notch1 signaling." (PMID 28881855, 2017). "On the other hand, from an ING-GAS mouse model infected with H. pylori, it was revealed that methylation silencing of Dll1 has the ability to control Notch1 activity in gastric cancer." (PMID 28881855, 2017). "From clinical gastric cancer specimens, the expression of Notch1 and Jagged1 are tightly correlated with the phosphorylation level of STAT3 and the expression level of Twist." (PMID 28881855, 2017). "miR-935 controls proliferation, migration and invasion of gastric cancer cells by downregulating Notch1 expression." (PMID 28881855, 2017). "High Notch1 expression is an independent poor prognostic factor in many other cancers, such as breast and gastric cancer." (PMID 28060745, 2017). "In summary, DLL4 is associated with CSPCs in gastric cancer, and its expression impacts CSPC stemness characteristics associated with the Notch‐1 pathway including self‐renewal, differentiation, proliferation, chemoresistance, and tumor formation." (PMID 27891816, 2017). "There is a strong correlation between the expression level of Notch2 and the development of gastric carcinoma and a reasonable relationship between Notch1 upregulation and intestinal-likephenotypes of gastric lesions." (PMID 28881855, 2017). "More studies have explored the role of Notch1 in gastric carcinoma compared to other components of Notch signaling." (PMID 28881855, 2017). "In this report, Notch1′s high mRNA expression was found to be correlated to worsen OS for all gastric cancer patients followed for 20 years." (PMID 27363496, 2016). "CD133 is considered as a stem-like cell marker in some cancers including gastric cancers, and Notch1 signaling is known to play an important role in the maintenance and differentiation of stem-like cells." (PMID 27489358, 2016). "Here, we show that RKIP activity in cervical and stomach cancer is inversely correlated with endogenous levels of the Notch1 intracellular domain (NICD), which stimulates the epithelial to mesenchymal transition (EMT) and metastasis." (PMID 26716415, 2016). "Notch1′s high mRNA expression was found to be correlated to worsen OS for all gastric cancer patients followed for 20 years, HR 1.38 (1.16–1.64), p = 0.00022." (PMID 27363496, 2016). "In this study, we aimed to investigate the expression of the stem-like cell marker CD133 in gastric cancers, and to clarify the role of Notch1 pathway on cell proliferation, tumorigenesis and induction of CD133 in diffuse type gastric cancers." (PMID 27489358, 2016). "In gastric cancer cells, Notch1 and Notch2 receptor intracellular domains (N1IC and N2IC, respectively) enhance carcinogenesis through up-regulating cyclooxygenase-2." (PMID 26041881, 2015).
gastric cancer (continued). "A previous study has shown that abnormal Notch1 signaling contributes to the development and occurrence of gastric cancer." (PMID 24396472, 2014). "The Notch receptor family encompasses four members, and NOTCH1 and NOTCH2 have been implicated to enhance gastric cancer progression." (PMID 22970250, 2012). "This is consistent with published findings that DLL1 controls Notch 1 activity in mouse intestinal tissue and Notch 1 activation in patients with intestinal-type of gastric cancer." (PMID 22249198, 2011). "For this purpose, we evaluated the Notch1 cascade in gastric cancer cell lines and we found a specific correlation between DLL1 expression and promoter hypermethylation." (PMID 22249198, 2011). "This study shows that Notch1 activity in gastric cancer is controlled by the epigenetic silencing of the ligand DLL1, and that Notch1 inhibition is associated with the diffuse type of gastric cancer." (PMID 22249198, 2011). "In addition, overexpression of SIRT3 significantly inhibited the proliferation ability and colony formation number of gastric cancer cells by downregulating Notch-1, and inhibited the proliferation of gastric cancer cells." (PMID 40943150, 2025). "Similarly, circ‐NOTCH 1 antagonizes miR‐449c‐5p availability to facilitate MYC‐induced NOTCH 1 overexpression that eventually leads to induction of metastasis and stem cell properties in gastric cancer." (PMID 40761890, 2025). "A recent study demonstrated that Penicilazaphilone C could induce apoptosis in gastric cancer by blocking the notch receptors, Notch1 and Notch2." (PMID 36768307, 2023). "Thus, it was suggested that Luteolin inhibited angiogenesis and vasculogenic mimic formation in gastric cancer cells by suppressing VEGF secretion based on the Notch1 expression." (PMID 36992138, 2023). "Furthermore, the introduction of Notch1 also curbed the augmentation of gastric cancer cell proliferation, migration, and drug resistance by the supernatant from IGF2BP2 overexpression MSCs." (PMID 37865637, 2023). "Furthermore, the co-transfection of Notch1 inhibited the stimulatory effects of the supernatant from CSF2 overexpression MSCs on gastric cancer cell proliferation, migration and drug resistance." (PMID 37865637, 2023). "Moreover, activating the Notch1 pathway contributes to enhancing the resistance of gastric cancer cells to chemotherapy." (PMID 35655918, 2022). "In addition, CD44, Wnt2, Bmi1, Notch1, Oct4, Sox2, Nanog, C-mys, ABCG2, CXCR4 and other “stemness associated genes” are highly expressed in the CD44+ gastric cancer cell population." (PMID 36316684, 2022). "It is reported that Notch1 is correlated with immune infiltrates in gastric cancer." (PMID 36119057, 2022). "Moreover, linc00641 sponged the expression of miR-429 and subsequently upregulated Notch-1 expression in gastric cancer cells." (PMID 33714199, 2021). "In conclusion, LINC00641 can function in gastric cancer by targeting miR-429/Notch-1 axis." (PMID 35155216, 2021). "The role of Notch-1 in gastric cancer has been characterized in recent years." (PMID 33714199, 2021). "Finally, the experiment proved that LINC00641 increased the expression of Notch-1 by competitive binding to miR-429 and increased the biological behaviors of gastric cancer cell proliferation, migration and invasion." (PMID 35155216, 2021). "Expression of Notch1 and Notch2 decreases after gastric cancer resection." (PMID 34234838, 2021). "This phenomenon may be related to the inhibition of Notch1/Hes1 signaling pathway; it provides a potential therapeutic method to improve the chemosensitivity of 5-FU in gastric cancer." (PMID 34257696, 2021). "Overexpression of Notch-1 prevents gastric cancer cells from undergoing TNFα-mediated apoptosis." (PMID 33714199, 2021). "Overall, this study provides evidence that Notch1/2/3/4 could become the potential targets for precision treatment and new biomarkers in the prognosis of gastric cancer." (PMID 32028262, 2020).
gastric cancer (continued). "Recent studies have shown that Sirt3 could downregulate Notch1 in human gastric cancer, and Notch1 overexpression attenuated the inhibitory effect of Sirt3 on the proliferation of tumor cells." (PMID 29311941, 2017). "Notch1 pathway-mediated microRNA-151-5p promotes gastric cancer progression." (PMID 28030818, 2017). "miR124 negatively regulates Notch1 signaling by targeting Jagged1 in gastric cancer cells." (PMID 28881855, 2017). "miR935 inhibits gastric carcinoma cell proliferation, migration and invasion by targeting Notch1." (PMID 28881855, 2017). "To assess this hypothesis, we developed a gastric cancer cell line whose Notch1 could be knocked-down by addition of doxycycline (Dox) to the culture (N1KOK3)." (PMID 27489358, 2016). "In the context of gastric cancer progression, activated Notch1 signaling occurred through COX-2." (PMID 27381829, 2016). "We aimed to investigate whether Notch1 signaling contributes to the carcinogenesis of gastric cancers and CD133 induction." (PMID 27489358, 2016). "Indeed our result showed that poorly-differentiated gastric cancer cells expressed not only CD133 but also activated-Notch1." (PMID 27489358, 2016). "Their results supported that Notch1 expression indicated good prognosis in gastric cancer patients." (PMID 27363496, 2016). "Furthermore, our results suggested that Notch1 signaling is required for maintaining the stem-like cell population, proliferation and anchorage independent growth in gastric cancers." (PMID 27489358, 2016). "In the current study, we accessed the prognostic roles of four Notch receptors, Notch 1–4, in gastric cancer patients through “The Kaplan-Meier plotter” (KM plotter) database, in which updated gene expression data and survival information include a total of 876 gastric cancer patients." (PMID 27363496, 2016). "Activated Notch1 pathway could augment progression of gastric cancer cells through miR-151-5p and FAK." (PMID 27191259, 2016). "In gastric cancer cells, Notch1 and Notch2 pathways have been shown to promote tumorigenesis." (PMID 27191259, 2016). "In gastric cancer (GC), NOTCH1 and NOTCH2 are believed to contribute to tumor progression." (PMID 25954607, 2015). "The activated Notch1 signal pathway has been shown to be involved with gastric cancer progression." (PMID 23898884, 2013). "Recently, a similar role of NALT1 was reported in gastric cancer (GC), where the knockdown of this lncRNA resulted in a decrease in NOTCH1 expression, which reduced the invasion and migration of GC cells." (PMID 37628760, 2023). "Indeed, we observed that Notch-1 overexpression promoted the viability of gastric cancer cells, while silencing Notch-1 had the opposite effect, suggesting that Notch-1 is a pivotal factor in the regulation of gastric cancer cell viability." (PMID 33714199, 2021). "Moreover, overexpression of linc00641 increased the expression of Notch-1 in gastric cancer cells." (PMID 33714199, 2021). "Therefore, linc00641 performs its functions in gastric cancer in part via upregulation of Notch-1." (PMID 33714199, 2021). "Additionally, Notch1, Notch3, Jagged1, Jagged2 and Hes1 are expressed primarily at the isthmus of gastric mucosa, based on immunohistochemical analysis, and are expressed significantly less in normal gastric tissue compared to gastric cancer tissues." (PMID 28881855, 2017). "The aim of the present study was to delineate Notch1 expression in gastric cancer (GC) and its function in GC EMT." (PMID 24932308, 2014). "In conclusion, Notch1 may be a novel target for gastric cancer therapy." (PMID 24396472, 2014). "Our results provide evidence that Notch1 activation in GC is controlled by the epigenetic silencing of the ligand DLL1, and that Notch1 inhibition is associated with the diffuse type of gastric cancer." (PMID 22249198, 2011).
gastric cancer (continued). "In gastric cancer, ELK4 activates lncRNA SNHG22 transcription to inhibit tumor suppressor expression and upregulate the Notch1 signaling, facilitating cell proliferation and invasion." (PMID 41502523, 2025). "In gastric cancer, simultaneous blockade of Notch (using DAPT) and PI3K/Akt signaling (using LY294002) can synergistically inhibit the expression of Notch1, Hes1, and p-Akt, significantly suppressing tumor metastasis." (PMID 40755759, 2025). "Specifically, it can inhibit angiogenesis in gastric cancer by suppressing the secretion of VEGF, which depends on the expression of Notch1, ultimately leading to a reduction in the migration and proliferation of gastric cancer cells." (PMID 39314630, 2024). "By integrating the final data, SOD2, sulfiredoxin 1 (SRXN1), neurogenic locus notch homolog protein 1 (NOTCH1), and mitogen-activated protein kinase 14 (MAPK14) were predicted to be the target genes for the anti-gastric cancer effects of WNG." (PMID 39252074, 2024). "In gastric cancer cell lines (SGC7901/DDP and BGC823/DDP), NOTCH1 was shown to promote the evolution of cisplatin-resistant cells via the upregulation of lncRNA AK022798, while its downregulation using siRNAs reduced the expression of drug resistance genes." (PMID 37628760, 2023). "Correspondingly, co-inhibition of Notch1 in P-MSCs reversed the effects of IGF2BP2 knockdown on MSCs reprogramming, as well as the effects of their supernatants on gastric cancer cell proliferation, migration, and drug resistance." (PMID 37865637, 2023). "Notch1 co-transfection partially reversed the effects of CSF2 on MSC phenotype and function, including the tropism towards gastric cancer cells, the enhanced FAP and α-SMA expression, and the secretion of GM-CSF, FGF, and PDGF-BB." (PMID 37865637, 2023). "Its anticancer effects were achieved by reducing Notch1, p-PI3K, p-AKT, p-mTOR, p-ERK, and p-STAT3 and increasing p-P38 signaling in gastric cancer cells." (PMID 36992138, 2023). "Myc is also a target for miR-449c-5p and circNOTCH1, upregulated in gastric cancer and promotes tumor growth and metastasis by interfering with miR-449c-5p/MYC/NOTCH1 axis." (PMID 35626752, 2022). "Overexpressed SNHG1 positively regulates Notch 1 and Doublecortin-like kinase 1 (DCLK1) expressions via modulation of miR-15b, inducing EMT in gastric cancer." (PMID 36229883, 2022). "LY294002 in coordination with DAPT (γ-Secretase Inhibitor) inhibits Notch1, HES1, and pAkt in gastric cancer cells, thus inhibit metastasis of gastric cancer through mutual enhancement." (PMID 33958005, 2021). "MiR-15b targets DCLK1 to regulate the expression of Notch1 and inhibit the EMT process of gastric cancer cells." (PMID 34422902, 2021). "In gastric cancer, the AKT1/NF-kB/Notch1/PTEN axis had a significant role in the development of chemoresistance." (PMID 32028262, 2020). "In summary, lncRNA SNHG1 can regulate the effects of DCLK1/Notch1 on the EMT process and cell migration in gastric cancer through miR-15b regulation, providing a novel potential target for GC treatment and also new hope for GC patients." (PMID 32423385, 2020). "Activation of the Notch1-COX-2 and Notch2-COX-2 signaling axes is also a pivotal event in promoting gastric cancer progression partly through Cyclooxygenase-2." (PMID 28881855, 2017). "Activated Notch1 pathway enhanced FAK promoter activity and promoted FAK and miR-151 expressions in gastric cancer cells." (PMID 27191259, 2016). "Activation of Notch1 pathway enhanced expressions of miR-151 and its host gene, focal adhesion kinase (FAK), in gastric cancer cells." (PMID 27191259, 2016).